IGF1 (insulin like growth factor 1)
Diseases named in the same sentence as IGF1 in open-access papers (continued):
Sharing a sentence is not in itself a finding about the gene and the disease.
cancer (continued). "On the contrary increased levels of IGF-1 reverse cancer prevention due to CR in mice probably stimulating cell proliferation and inhibiting apoptosis." (PMID 24883306, 2014). "Among the subjects with a history of cancer, the median survival was 49.6 months in the group with low IGF-1 and 20.7 months in the group with a high IGF-1 (P < 0.01)." (PMID 24618355, 2014). "Upon stimulation with IGF-1 that promotes cell migration and cancer metastasis, APP-kd cells migrate slowly in response to IGF-1 partly due to limited activation of AKT." (PMID 25491510, 2014). "Men on ADT most likely had a more severe tumour and thus lower life expectancy, which is also reflected in the analysis for IGF-1 related cancer stratified by tumour stage." (PMID 25047238, 2014). "Within the microenvironment, the stromal Hospicells, in concert with IGF-1, provide strong synergetic effect for the maintenance and proliferation of cancer cells." (PMID 25095896, 2014). "Many GPCRs and their cognate agonists also mediate autocrine/paracrine growth stimulation in a variety of cancer cells and dramatically synergize with insulin/IGF-1 in inducing mitogenic signaling." (PMID 25295009, 2014). "High IGF1R expression levels and elevated circulating IGF1 levels have been demonstrated to be correlated with improved response to IGF1R-targeted therapies in clinical trials of malignant tumors." (PMID 25289085, 2014). "In this study, we showed that glucosamine effectively inhibits IGF-1R-mediated Akt signal transduction in various human carcinoma cell lines by both suppressing IGF-1-induced IGF-1R activation and reducing IGF-1R protein stability." (PMID 24438088, 2014). "Excess autocrine/paracrine production of IGF-1 and IGF-2 and/or low IGFBP3 levels are associated with an increased cancer risk of several cancers including breast, endometrial and bladder." (PMID 23826179, 2013). "Activation of AMPK inhibits the mammalian target of rapamycin (mTOR), a protein known to be a driver of cellular survival and proliferation in human cancer and one that is activated by IGF-1." (PMID 24133632, 2013). "After testing 10 samples from each group using ELISA, we observed that primary cancer cell lines had consistently higher levels of IGF-1 in both cell lysates and cell culture medium than normal epithelial ovarian cell lines (P<0.05)." (PMID 24103397, 2013). "Recent studies demonstrated that SNPs or haplotypes in other regions in the IGF-1, especially downstream of the CA repeats, were associated with circulating IGF-1 levels or cancer susceptibility." (PMID 23530598, 2013). "Deregulation of the IGF signaling pathway frequently occurs in human cancer and involves the establishment of autocrine loops comprising IGF-1 or IGF-2 and/or IGF-1R over-expression." (PMID 23525758, 2013). "This is an important therapeutic criterion as all human cancers are exposed to IGF-1 and IGF-2 due to hepatic endocrine synthesis, tumor stroma expression, and autocrine activation." (PMID 23383308, 2013). "Paradoxically, a number of studies have demonstrated positive effects of IGF-1R and IGF-1 in conferring radiation resistance, mostly through prevention of apoptosis in some cancer cell types." (PMID 24205274, 2013). "First, IGF-1 is known to act as an important growth factor regulating proliferation and apoptosis of cancer cells and has a role in an acquisition of resistance to endocrine therapies." (PMID 23530598, 2013). "The HGF/cMET axis presents a well-established cross-talk with IGF1 and its receptor IGF1R, which are both implicated in the development and progression of a variety of human cancers." (PMID 24005867, 2013). "These were originally developed for use in cancer treatment to antagonize IGF-1 mediated mitogenic signaling." (PMID 23443494, 2013).
cancer (continued). "Meanwhile, a cytosine-adenine (CA) repeat polymorphism has been known to be located in the promoter region of the IGF-1 gene and many studies investigated the influence of the polymorphism on the circulating IGF-1 level and risk for certain types of cancer." (PMID 23530598, 2013). "The authors demonstrated that metformin can act through IGF-1-independent mechanisms by promoting the systemic inhibition of circulating growth factors and local receptor tyrosine kinase signaling in cancer tissues." (PMID 23986086, 2013). "High IGF-1 plasma concentrations and the presence of IGF-1R on the cell surface are found in many cancers, but in the case of EC, the role of circulating IGF-1 is controversial." (PMID 24308813, 2013). "DER produces anti-cancer effects through several metabolic pathways, including inhibition of the IGF-1/PI3K/Akt/HIF-1α pathway which is used by cancer cells to promote proliferation and angiogenesis and inhibit apoptosis." (PMID 23755243, 2013). "The proliferative effects of insulin are believed to be an indirect effect through increasing levels of bioavailable IGF-1, and the role of IGF-1 as a risk factor for cancer has been well established." (PMID 23819063, 2013). "Epidemiological studies show that high levels of IGF1 and low levels of IGFBP3 are associated with an increased risk for several common cancers, including cancer of the prostate, breast, lung, and colorectum." (PMID 23527244, 2013). "In these analyses, both capture antibodies revealed a concordant and significant (p<0.05) difference in abundance of IGF1 (decreased in cancer) and IGFBP2 (increased in cancer), as shown in." (PMID 24282616, 2013). "The data implicating IGF-1 and IGF-2 in cancer risk and tumor progression have positioned IGF1R as a prime oncolgy therapeutic target, anticipated to have activity against a number of human malignancies." (PMID 23383308, 2013). "The increase in insulin and IGF-1 are considered mitogenic factors contributory to cancer development." (PMID 24308813, 2013). "Several case control studies have demonstrated a possible link between IGF-1 bioactivity and different cancers including prostate, colorectal, and breast." (PMID 22853725, 2012). "Consistent with studies indicating that inhibition of IGF1 signaling is required for starvation-mediated sensitization of cancer cells to therapeutic drugs, we observed a decrease of AKT phosphorylation upon serum starvation." (PMID 23211021, 2012). "In accordance with observed cancer-protective effects of low IGF-1 signaling is a recent epidemiological study, which demonstrated that high serum IGF-1 concentrations were associated with increased cancer deaths in older men." (PMID 22891897, 2012). "Reduced insulin and IGF-1 signaling has been associated with animal and human longevity.On the other hand, inhibition of insulin/IGF-1 signaling is one anti-cancer strategy under intensive investigation." (PMID 23455653, 2012). "In other words, overexpression of IR serves as a major mechanism of IGF1R signaling in cancer cells by enabling the formation of more heterodimers which are available for binding ligands including IGF1, IGF2, and insulin." (PMID 22438913, 2012). "In vitro, insulin stimulates the growth of cancer cells, through the interaction with insulin-like growth factor-1 (IGF-1) receptors and its own receptors." (PMID 23209929, 2012). "Insulin is an important growth factor for colonic mucosal cells and colonic carcinoma cells in vitro, while IGF-1 inhibits apoptosis and promotes cell cycle progression, leading to the development of cancer." (PMID 23304125, 2012). "Another group found that IGF1 is likely to be secreted from normal genomically stable cells towards the cancer cells, thereby acting in a paracrine manner." (PMID 22880013, 2012). "Following studies showed that GIPC is involved in IGF1 induced proliferation of different cancer cell lines and cancer cell survival." (PMID 22693602, 2012).
cancer (continued). "IGF-1 is a potential mitogen and inhibitor of apoptosis and also can promote tumorigenesis in various cancer model systems." (PMID 22839452, 2012). "Lower IGF-1 signaling due to mutations with reduced activity of the IGF-1 receptor are associated with longevity and lower incidence rates of cancer." (PMID 22891897, 2012). "The European Prospective Investigation into Cancer and Nutrition clearly confirmed the correlation between increased dairy protein consumption and raised IGF-1 serum concentrations in adults." (PMID 22891897, 2012). "The same research group also demonstrated that statins reduced cancer risk in DM patients, potentially via normalizing hydroxymethylgutaryl-CoA reductase (HMGCR) and the insulin-like growth factor-1 (IGF-1) signaling pathway." (PMID 23234464, 2012). "Exogenous IGF-1 also rescued the expression of several metabolism- and cancer-related genes affected by CR in the mammary gland." (PMID 23342276, 2012). "Inhibition of IGF1 signaling was required for starvation-mediated protection of normal cells and sensitization of cancer cells to therapeutic drugs." (PMID 23211021, 2012). "Involvement of IGF-1 in cancer is further supported by its ability to enhance the growth of a variety of cancer cell lines." (PMID 22934068, 2012). "But practically, there were also some epidemiological studies showing null association between circulating IGF-1 and IGFBP-3 levels and cancers." (PMID 23185474, 2012). "Above on, an elevated level of circulating IGF-1 and/or a lower level of IGFBP-3 was related to the increased risk of cancers, and this was supported by some studies in breast, prostate and colorectal cancers." (PMID 23185474, 2012). "Exogenous IGF-1 rescued the expression of several metabolism- and cancer-related genes affected by CR in the mammary gland." (PMID 23342276, 2012). "Third, high plasma glucose concentrations elevate the levels of circulating insulin and free IGF1, two potent anti-apoptotic and growth factors for most cancer cells." (PMID 22029671, 2011). "Evidence exists that chronically elevated blood glucose, insulin and IGF1 levels facilitate tumorigenesis and worsen the outcome in cancer patients." (PMID 22029671, 2011). "IGF-1 has a well-established role in the metastasis of cancer cells in vivo, as well as stimulating growth in vitro, and alveolar macrophages produce high levels of IGF-1 in response to quartz dust-induced lung injury." (PMID 21699731, 2011). "Emphasis will be placed on the role of insulin and IGF1 signaling in tumorigenesis as well as altered dietary needs of cancer patients." (PMID 22029671, 2011). "Involvement of theIGF-1/AKT pathway in cancer cachexia was confirmed by our data showing decreased AKT activation as evidenced bydown-regulated IGF-1, IRS-1 and IGFBP5." (PMID 21069263, 2011). "IGF-1 has been shown to elevate cancer cell proliferation via elevation of ROS (reactive oxygen species)." (PMID 21849056, 2011). "Western blotting analyses confirmed the suppression or elevation of these proteins in HT-29 cancer cells treated with RSV or IGF-1, respectively." (PMID 21849056, 2011). "IGF–1 is also expressed in many tumor cell lines and had a role in both normal cell proliferation and in the growth of cancers." (PMID 22514573, 2011). "Ultimately, then, the importance of IGF-1 signaling can vary tremendously across cancer types and even temporally within a patient's tumor if selective pressure is applied through therapeutic targeting." (PMID 24212944, 2011). "Because the expression levels and regulation of IGF-1 affect cancer formation and progression, IGF-1 homeostasis in the microenvironment is crucial to the maintenance of the proper cellular proliferative and inhibitory activity." (PMID 23675206, 2010). "One caveat of the IGF-1 pathway is that reduced signaling increases longevity, whereas, enhanced signaling promotes cancer." (PMID 20505758, 2010).
cancer (continued). "Of note, both murine Laron dwarfs and human Laron dwarfs with chronically low Igf-1 levels are significantly protected from developing cancer." (PMID 21084728, 2010). "Further studies are also needed to link the effect of chronic high Igf-1 signaling in VSELs with the development of cancer." (PMID 21084728, 2010). "This study suggests a new and interesting link between DPP-IV and IGF-1 in the development of cancer in a specific tumor niche." (PMID 23675206, 2010). "Whereas non-SP cells formed fewer and slower-growing tumours, SP cells over-expressed many genes associated with cancer stem cell and drug resistance: ABCG2, FGF1, IGF1, MYC, SOX1/2, WNT1, as well as genes involved in angiogenesis, Notch and Hedgehog pathways." (PMID 20424609, 2010). "Lycopene has been shown to inhibit proliferation of several types of cancer cells through arrest of tumor cell-cycle progression, IGF-1 (insulin-like growth factor 1) signaling transduction, and induction of apoptosis." (PMID 22254062, 2010). "The insulin like growth factor (IGF)-1 is a potent mitogen for many cancer cell lines and the stimulation of IGF-1 receptor is necessary for proliferation of many cells in vivo and in vitro, often in conjunction with other growth factors." (PMID 20565977, 2010). "Since 2001 several more reports of a relationship between IGF-1, IGF-1 receptors, and cancer risk have been published as well as associations between IGF-2 and IGF-2 receptors and cancer risk." (PMID 20617018, 2010). "The Cancer Pathway Finder Array analysis identified numerous cancer-associated genes exhibiting substantial over expression in trisomic BG01V APCs relative to diploid H9 APCs, including CDC25A, IGF1, MMP9, FGFR2, BRCA1, CASP8 and TERT1." (PMID 20423517, 2010). "The epidermal growth factor (EGF) family of proteins, and in particular HER2, promote androgen independent cancer growth, as can fibroblast growth factors and insulin-like growth factor-1 (IGF-1)." (PMID 20406442, 2010). "The IGF signalling pathway is activated in various cancers, and monoclonal antibodies targeting IGF1R have been recently developed; IGF1R is a transmembrane tyrosine kinase receptor, and both IGF1 and IGF2 are ligands for IGF1R." (PMID 19034281, 2008). "It’s role in EGF and IGF-1 signaling and increased secretion in cancer however, indicate that it plays a significant role in endometrial carcinogenesis and therefore is a rationale target for development of drugs and biomarker panels." (PMID 19784388, 2008). "In contrast, studies using synthetic oral ghrelin mimetics have shown a significant effect on the IGF-1 level in volunteers and in the frail elderly or patients with cancer cachexia." (PMID 18182992, 2008). "Scientists have contributed to investigating the correlation of serum IGF-1 or IGFBP-3 to the prevalence of a variety of cancers, but have given diverse results." (PMID 18781172, 2008). "Full blown cancer cells utilize growth factors such as IGF1 to overcome stress or pro-apoptotic signals, by re-igniting the downstream pathways." (PMID 17622350, 2007). "The IGF-1 signaling system plays a crucial role in tumor transformation, malignant cell turn over and survival of cancer cells." (PMID 17953765, 2007). "Insulin-like growth factor-1 levels inscribe a gene expression profile for angiogenic factors and cancer progression in breast epithelial cells." (PMID 15756256, 2005). "IGF-1 has been described to facilitate tumorigenesis and metastatic spread in other cancers." (PMID 40017592, 2025). "Based on the various microRNAs studied, it was concluded that microRNA and, consequently, IGF-1 pathway deregulation might be important for the cell transition from chronic inflammation to cancer." (PMID 41153350, 2025). "The IGF-1 system regulates cell growth, differentiation and energy metabolism and thus plays a crucial role in the modulation of key aspects of cancer biology, such as cancer cell growth, survival, transformation and invasion." (PMID 41153350, 2025).
cancer (continued). "The control of the IGF-1/IGF-1R signaling pathway by microRNAs is essential for many physiological functions and is closely associated with the development, progression and response to treatment of several cancer types." (PMID 41153350, 2025). "MTF's modulation of insulin and IGF‐1 signaling may influence the interactions between cancer cells and surrounding stromal cells, immune cells, and blood vessels within the tumor microenvironment." (PMID 39969135, 2025). "The other mRNA isoforms, IGF1-Eb and IGF1-Ec, and their corresponding pro-peptides may be overexpressed in different human cancers." (PMID 39796756, 2025). "Furthermore, irisin has been reported to influence IGF-1 signalling, which plays a critical role in cancer development by promoting mitogenic and anti-apoptotic pathways." (PMID 41002741, 2025). "Likewise, fibroblast-derived IGF1 can induce epithelial–mesenchymal transition in cancer cells, contributing to therapy resistance." (PMID 41275311, 2025). "The nuclear effects of IGF-1 correlate with cancer cell biology." (PMID 41272918, 2025). "Additionally, these antagonists reduce the production of tumoral IGF1, a key player in tumorigenesis and cancer progression." (PMID 40244089, 2025). "It is hypothesized that a FMD may promote cancer prevention in mouse models by reducing levels of IGF-1, insulin, leptin, glucose, visceral fat, and other disease and aging markers." (PMID 39940361, 2025). "The synthesis of IGF-1 is regulated, among other factors, by microRNAs (miRNAs), and it has been shown that the miRNA-induced regulation of IGF-1 is implicated in various stages of tumor development and/or progression in different types of cancer." (PMID 41153350, 2025). "In particular, tirzepatide may increase the synthesis of insulin, IGF-1, IGF-2, and their binding proteins—factors that have been linked to elevated cancer risk, especially in patients with prior pancreatic injury." (PMID 41310711, 2025). "Greater adult body height may be related to increased exposure to insulin-like growth factor 1, which may influence cancer development by inhibiting apoptosis and stimulating proliferation, adhesion, and cell migration." (PMID 40723159, 2025). "IGF1 receptor antagonists or IGF1 signaling inhibitors, which are already under investigation for various cancers, may be particularly beneficial for individuals with long telomeres and elevated IGF1 levels." (PMID 41444654, 2025). "Autocrine IGF-1 may further drive tumor-mediated platelet “education,” with cancer signals altering RNA splicing to increase IGF-related transcripts." (PMID 41226816, 2025). "Ginsenoside F1 can play an anti-cancer role by regulating insulin-like growth factor 1 (IGF-1)." (PMID 40271065, 2025). "In addition, high levels of miR-190 have been detected in cancer tissues, and as miR-190b expression increases, IGF-1 expression decreases." (PMID 41153350, 2025). "In this process, neutrophil-derived cathepsin G activates insulin-like growth factor-1 to promote the entry of cancer cells into the bloodstream, while NETs can capture circulating cancer cells and promote the colonization of cancer cells in distant organs." (PMID 40131539, 2025). "However, the outcomes of clinical trials investigating the use of anti-IGF-1 antibodies in cancer patients are conflicting." (PMID 41383600, 2025). "Additionally, IGF-1 and its receptor play a critical role in mediating GH signaling and exertion of mitogenic and anti-apoptotic effects in cancer." (PMID 40806252, 2025). "Unlike other malignancies where higher IGF-1 levels might indicate a higher risk of cancer progression, HCC patients typically have lower serum IGF-1 levels." (PMID 39624154, 2025). "One of the most well established effects of fasting is a significant reduction in circulating levels of IGF-1, which plays a crucial role in promoting cellular proliferation and inhibiting apoptosis, with elevated levels of IGF-1 being linked to increased cancer risk." (PMID 39940361, 2025).